MORC3 (MORC family CW-type zinc finger 3)
Description:
Nuclear matrix protein which forms MORC3-NBs (nuclear bodies) via an ATP-dependent mechanism and plays a role in innate immunity by restricting different viruses through modulation of the IFN response. Mechanistically, possesses a primary antiviral function through a MORC3-regulated element that activates IFNB1, and this function is guarded by a secondary IFN-repressing function. Binds RNA in vitro. Histone methylation reader which binds to non-methylated (H3K4me0), monomethylated (H3K4me1), dimethylated (H3K4me2) and trimethylated (H3K4me3) 'Lys-4' on histone H3. The order of binding preference is H3K4me3 > H3K4me2 > H3K4me1 > H3K4me0. (Microbial infection) May be required for influenza A transcription during viral infection.
Synonyms: KIAA0136; NXP2; ZCWCC3; ZCW5
Tractability: Small molecule: a structure with a bound ligand is known. PROTAC: UniProt records ubiquitination sites on it; ubiquitination databases record sites on it; its protein half-life has been measured.
Gene: Protein-coding gene on chromosome 21 (36,320,189 to 36,386,148, forward strand). Ensembl gene ENSG00000159256.
Subcellular location: Nucleus, nucleoplasm; Nucleus matrix; Nucleus, PML body; Chromosome
Subcellular location (Human Protein Atlas): Nucleoplasm; Mitochondria
Gene Ontology:
Molecular function: DNA binding; histone H3K4me3 reader activity; protein binding; protein-macromolecule adaptor activity; ATP hydrolysis activity; zinc ion binding
Biological process: antiviral innate immune response; maintenance of protein location in nucleus; negative regulation of fibroblast proliferation; negative regulation of interferon-beta production; negative regulation of transcription by RNA polymerase II; peptidyl-serine phosphorylation; positive regulation of cellular senescence; protein phosphorylation; protein stabilization; chromatin organization
Cellular component: chromatin; nuclear matrix; nucleoplasm; PML body; chromosome; nucleus
Genetic constraint (gnomAD): Loss-of-function variants: 27 observed, 100.56 expected, observed/expected ratio (o/e) 0.27, 90% interval 0.2 to 0.37. The upper end of that interval is the gene's LOEUF score, 0.37, which puts it in group 1 of 6, group 1 being the genes least tolerant of losing a copy. Missense variants: 812 observed, 1,092.6 expected, observed/expected ratio (o/e) 0.74, 90% interval 0.7 to 0.79. Synonymous variants: 369 observed, 370.37 expected, observed/expected ratio (o/e) 1, 90% interval 0.91 to 1.09.
Homologues: Orthologues: chimpanzee MORC3 (99% identical), macaque MORC3 (98% identical), dog MORC3 (91% identical), rabbit MORC3 (90% identical), pig MORC3 (88% identical), guinea pig MORC3 (85% identical), rat Morc3 (84% identical), mouse Morc3 (83% identical), zebrafish morc3a (45% identical), tropical clawed frog MORC3 (28% identical). Paralogues in human: MORC4 (35% identical).
Diseases named in the same sentence as MORC3 in open-access papers:
MORC3 is named in the same sentence as 78 diseases in open-access papers, as found by Europe PMC text mining. Sharing a sentence is not in itself a finding about the gene and the disease. The quoted sentences say what the papers report.
myositis (87 papers, 2014 to 2026). "For example, anti-MORC3 antibody has been confirmed as one of the major myositis-specific autoantibodies, which are essential in identifying clinically homogeneous subsets and predicting the prognosis of idiopathic inflammatory myopathies (IIMs) (such as polymyositis and DM)." (PMID 34839357, 2021).
dermatomyositis (56 papers, 2013 to 2026). Dermatomyositis (DM) is a type of idiopathic inflammatory myopathy characterized by evocative skin lesions and symmetrical proximal muscle weakness. "MORC3 has been reported to correlate to an increased cancer risk in patients with dermatomyositis (DM)." (PMID 34839357, 2021). "In addition, dermatomyositis patients with anti-MORC3 autoantibody have an increased frequency of cancer compared to those without the anti-MORC3 autoantibody." (PMID 39329063, 2024).
HCMV infection (3 papers, 2020 to 2023). "Whilst these changes are small, the decreases in MORC3 RNA in infected, differentiated cells is consistent with previous reports that MORC3 is downregulated during HCMV infection in differentiated cells." (PMID 38009611, 2023). "Additionally, MORC3’s antiviral role extends to HCMV infection as its plaque-forming efficiency increased in MORC3-depleted cells." (PMID 33530304, 2021). "However, a proteomic screen to quantify protein degradation during the early phase of HCMV infection identified MORC3 to be degraded in a proteasomal manner, suggesting the activity of a viral countermeasure." (PMID 33530304, 2021). "Notably, this group contained the known HCMV restriction factors Sp100, MORC3, DAXX, and HLTF in addition to cell cycle regulating protein ANAPC1, all of which have been reported to be degraded during HCMV infection by ourselves and others." (PMID 33585265, 2020).
promyelocytic leukemia (3 papers, 2012 to 2024). "NXP-2/MORC-3 is found in the nucleus and in nuclear dots known as Promyelocytic Leukemia (PML) nuclear bodies." (PMID 38991369, 2024).
virus infection (3 papers, 2015 to 2023). "During the early stages of viral infection, it is possible that the host gene MORC3 interacts with nuclear IRF3 to potentially facilitate the degradation of phosphorylated IRF3." (PMID 38150467, 2023). "For example, endogenous NACC1 appeared more stable during mSLS4 than wt virus infection whereas MORC3 was equally sensitive to the two viruses." (PMID 26200910, 2015). "Consequently, our results indicate circMORC3 and host gene MORC3 can synergistically inhibit TRIF and IRF3 in the TLR signaling pathway at different stages of viral infection, promoting viral immune escape." (PMID 38150467, 2023).
COVID-19 (2 papers, 2022 to 2024). A disease caused by infection with severe acute respiratory syndrome coronavirus 2. "KEGG pathway enrichment analysis showed that MORC3 may regulate multiple virus-related pathways, including influenza A, hepatitis B, hepatitis C, COVID-19, Epstein-Barr virus, human papillomavirus, herpes simplex virus 1, and human immunodeficiency virus 1 (HIV-1)." (PMID 39329063, 2024).
osteoarthritis (2 papers, 2020 to 2024). A noninflammatory degenerative joint disease occurring chiefly in older persons, characterized by degeneration of the articular cartilage, hypertrophy of bone at the margins and changes in the synovial membrane. "A rare genetic variant in MORC4 has been associated with a 3.4 times increased risk of osteoarthritis (Open Targets Platform92, accessed 25.05.2022), and another MORC family member, MORC3, is involved in calcium homeostasis and maintenance of bone remodeling." (PMID 38594418, 2024).
bone metabolic disorders (1 paper, 2016). "Our findings establish Morc3 as a novel regulator of bone homeostasis and opens up new avenues for identifying potential treatments targeting bone metabolic disorders." (PMID 27188231, 2016).
diffuse large B-cell lymphoma (1 paper, 2021). "Specifically, mammalian MORC3 mutations are associated with immune system defects and human cancers such as bladder, uterine, stomach, lung, and diffuse large B cell lymphomas." (PMID 34706774, 2021).
Down syndrome (1 paper, 2024). "MORC3 is also associated with autoimmune diseases and Down syndrome." (PMID 39329063, 2024). "Anti-MORC3 antibodies have been found in Down syndrome patients with cancer, and MORC3 is genetically changed in multiple cancers." (PMID 39329063, 2024).
head and neck cancer (1 paper, 2024). A primary or metastatic malignant neoplasm affecting the head and neck. "MORC3 was significantly downregulated in multiple cancers, including head and neck cancer, and low expression of MORC3 was associated with poor overall survival." (PMID 39329063, 2024). "The present data revealed new targets of MORC3 and elucidated the ability of MORC3 to suppress PD-L1 expression in head and neck cancer cells." (PMID 39329063, 2024). "The present study explored the expression levels of MORC3 mRNA in The Cancer Genome Atlas (TCGA) cancers and MORC3 protein in head and neck cancer." (PMID 39329063, 2024). "The present study demonstrated that IRF7 expression was negatively correlated with MORC3 in single head and neck cancer cells, which was correlated with the MORC3-mediated suppression of IRF7 expression." (PMID 39329063, 2024). "The expression levels of MORC3 and its target genes were further confirmed by single-cell RNA-seq analysis of head and neck cancer cells." (PMID 39329063, 2024). "However, the expression, roles, and targets of MORC3 in cancers, including head and neck cancer, remain largely unknown." (PMID 39329063, 2024). "The present study used the online CancerSEA database to analyze the expression of MORC3 and its target genes in head and neck cancer cells, which demonstrated a negative correlation between MORC3 and IFN-associated target genes, as well as between MORC3 and PD-L1." (PMID 39329063, 2024).
head and neck squamous cell carcinoma (1 paper, 2024). A squamous cell carcinoma that arises from any of the following anatomic sites: lip and oral cavity, nasal cavity, paranasal sinuses, pharynx, larynx, and salivary glands. "The expression correlation between MORC3 and these genes were analyzed at the single-cell level in head and neck squamous cell carcinoma using the GSE103322 database." (PMID 39329063, 2024). "In addition, male patients in TCGA head and neck squamous cell carcinoma (HNSCC) with high MORC3 expression showed significantly longer survival than those with low MORC3 expression." (PMID 39329063, 2024).
latent infection (1 paper, 2023). "We show, here, that this may be due, at least in part, to the ability of latent infection to upregulate MORC3 which, in turn, forms MORC3 NBs." (PMID 38009611, 2023). "We now show that, in contrast to lytic infection, MORC3 is upregulated during latent infection." (PMID 38009611, 2023). "Therefore, we next tested whether MORC3 NBs were disrupted during HCMV latency to redistribute MORC3 to alternative sites, perhaps for repression of the MIEP, or whether the MORC3 NBs remained intact in the presence of HCMV latent infection." (PMID 38009611, 2023). "We also show that MORC3 is induced during latent infection, recruited to the MIEP and forms MORC3 nuclear bodies (MORC3‐NBs) which, interestingly, co‐localize with viral genomes." (PMID 38009611, 2023). "Given that MORC3 is upregulated during latency, that MORC3 NBs are present during latent infection and that MORC3 is known to repress the MIEP, we next tested whether MORC3 or MORC3 NBs interact with viral genomes in latently infected cells." (PMID 38009611, 2023). "For instance, one important viral gene product expressed during latency, LUNA, is a known viral de‐SUMOylase and, consistent with this, latent infection results in de‐SUMOylation of MORC3; this MORC3 de‐SUMOylation is not observed in latent infection with viruses lacking LUNA." (PMID 38009611, 2023).
Obesity (1 paper, 2025). Accumulation of substantial excess body fat. "We found that MORC3, NUP62, CGAS, ABI3, and RPA2 were highly expressed in lean individuals, where as LMNA, ID2, CDKN1A, TENT4B, MME, and MYC were upregulated in the PBMCs of individuals with obesity." (PMID 40847086, 2025).
uterine cancer (1 paper, 2024). Primary or metastatic malignant neoplasm involving the uterine corpus and/or the cervix. "The expression of MORC3 in seven cancer tissues, including breast, kidney, lung, prostate, thyroid, or uterine cancers, was significantly lower compared to the expression in corresponding normal control tissues." (PMID 39329063, 2024).
cancer (42 papers, 2016 to 2025). A tumor composed of atypical neoplastic, often pleomorphic cells that invade other tissues. "In cancers, the function of MORC3 may be disturbed by an R420Q mutation in the CW domain, which decreases the binding of MORC3 to H3K4me3." (PMID 39329063, 2024). "Melanoma differentiation-associated protein 5 (anti-MDA-5), TIF-1, and NXP-2 cancer (also known as MORC3) are three novel DM-specific autoantibodies that may be useful in predicting the risk of developing cancer." (PMID 35415038, 2022). "The present study explored the expression of MORC3 in cancers at both transcriptional and translational levels." (PMID 39329063, 2024). "MORC3 knockdown also increased the expression of cellular proliferation-related genes and promoted cancer cell proliferation." (PMID 39329063, 2024). "The present study demonstrated that MORC3 regulates IFN-associated pathways and is a novel repressor of PD-L1 expression and cancer cell proliferation." (PMID 39329063, 2024). "The expression of MORC3 and its target genes were also analyzed in single cancer cells." (PMID 39329063, 2024). "MORC family CW-type zinc finger 3 (MORC3) is a transcriptional factor that regulates innate immune responses, but the expression and roles of MORC3 in cancers remain largely unknown." (PMID 39329063, 2024). "Thus, MORC3 may play important roles in suppressing the persistent activation of IFN-associated pathways, which may block the initiation and development of cancer." (PMID 39329063, 2024). "The expression of MORC3 was significantly lower in the nucleus where MORC3 is normally expressed, but not the cytoplasm, of OSCC cancer cells compared to epithelial cells in normal mucosal tissues." (PMID 39329063, 2024).
infection (8 papers, 2018 to 2025). The state of being infected such as from the introduction of a foreign agent such as serum, vaccine, antigenic substance or organism. "In the later stages of infection, the expression of MORC3 recovered, but the levels of circMORC3 increased." (PMID 40717901, 2025). "Knockdown of MORC3 can significantly enhance the expression levels of IRF3 upon SCRV infection while overexpressing MORC3 significantly inhibits the expression levels of IRF3 under SCRV infection." (PMID 38150467, 2023). "MORC3 is a cellular epigenetic factor whose expression is reduced during lytic infection for optimal IE gene expression." (PMID 38009611, 2023). "During WT HSV-1 infection, a high degree of colocalization between ICP0 and MORC3 was observed during the initial stages of infection prior to the degradation of SUMO-modified and unmodified MORC3." (PMID 31781083, 2019). "Thus we propose a balanced model of MORC3 upregulation during latency and downregulation during reactivation/lytic infection." (PMID 38009611, 2023). "This is in contrast to lytic infection where MORC3 is degraded to enhance MIEP activity." (PMID 38009611, 2023). "However, it is noteworthy that loss of MORC3 from cells that are normally non‐permissive did not result in a full lytic infection but, instead, led to an abortive infection." (PMID 38009611, 2023). "According to the findings reported by Wang and colleagues, during the infection process of the SCRV, in teleost fish, circMORC3 was observed to exhibit a different expression trend compared with its parental gene MORC3." (PMID 40717901, 2025). "In the early stages of infection, MORC3 was found to respond positively, whereas circMORC3 shown no visible change." (PMID 40717901, 2025). "However, the results showed that knockdown of MORC3 can significantly enhance the expression levels of ISG15, Mx1, Viperin, and IFN1 upon SCRV infection." (PMID 38150467, 2023). "How the MORC3 NBs are removed before reactivation is not yet known but it is known that during lytic infection, MORC3 is degraded, although again the viral protein required for this is not known." (PMID 38009611, 2023). "In addition, confocal experiments also showed that MORC3 and IRF3 are located in the nucleus under SCRV infection, suggesting that they may be related." (PMID 38150467, 2023).
tumor (7 papers, 2022 to 2026). "MORC3 deficiency downregulated the E-cadherin (CDH1) tumor suppressive gene and the keratin 14 (KRT14) epithelial differential marker but significantly upregulated the expression of oncogenic JUN, CCND1, CCND2, and CCN1 at the transcriptional level." (PMID 39329063, 2024). "Meanwhile, MORC3 expression was positively correlated with residual tumor (P = 0.007) and lymphatic invasion (P < 0.001), and MORC4 expression showed positive relation to N-stage (P = 0.001), M-stage (P = 0.015), and clinical stage (P < 0.001)." (PMID 39812044, 2025). "In summary, these findings suggested that MORC3 may act as tumor suppressor." (PMID 39329063, 2024). "Additionally, the MORC2 promoter methylation was markedly increased in CRC tissues (P < 0.05), but the methylation of MORC1, MORC3, and MORC4 was significantly lower in the tumor tissues than in negative controls." (PMID 39812044, 2025).
brain disorder (1 paper, 2024). A disease affecting the brain or part of the brain. "We found 7 variants that were associated with neurodevelopment and brain disorders, of which, 4 variants were found in both patients, namely in genes CTBP2, CDC27, UNC13D and IRF8, and 3 variants found in either of the patients, NDUFAF3, MRPS25, MORC3." (PMID 38638145, 2024).
MORC3 also shares sentences with these, for which no sentence is quoted: calcinosis (42 papers); juvenile dermatomyositis (14); myopathy (9); Skin ulcer (6); interstitial lung disease (5); autoimmune disease (4); breast carcinoma (4); Myalgia (4); idiopathic inflammatory myopathy (3); melanoma (3); dermatitis (2); Erythema (2); inclusion body myositis (2); juvenile polymyositis (2); polymyositis (2); rash (2); scleroderma (2); Skin rash (2); systemic lupus erythematosus (2); Areflexia (1); atherosclerosis (1); Atrophy (1); bladder tumor (1); ductal carcinoma (1); edema (1); endometrial cancer (1); gastric cancer (1); gestational diabetes mellitus (1); Hashimoto thyroiditis (1); hepatitis B (1).
A further 29 diseases each share a sentence with MORC3 in 1 paper.